CTSB (cathepsin B)
Diseases named in the same sentence as CTSB in open-access papers (continued):
Sharing a sentence is not in itself a finding about the gene and the disease.
ovarian cancer (15 papers, 2010 to 2025). A primary or metastatic malignant neoplasm involving the ovary. "The top three cancer types with mutated CTSB were prostate, esophagogastric, and ovarian cancers, while those with mutated CTSL were adrenocortical carcinoma, and esophagogastric and endometrial cancers." (PMID 35155389, 2022). "Six previous publications were found describing increased CTSB expression, content or activity in ovarian cancer compared to healthy tissue." (PMID 31484396, 2019). "In order to test the herein described cathepsin B degradable nanoparticles in vitro, we characterized two different ovarian cancer cell lines for the expression of this enzyme in comparison to human ovary." (PMID 31484396, 2019). "In this study, we investigated cathepsin B digestible particles for delivery of chemotherapeutics to ovarian cancer cells." (PMID 31484396, 2019). "According to the literature, cystatin C, as well as mature cathepsin B, were involved in the mechanism of invasion of ovarian cancer; however, this mechanism was not well understood." (PMID 23986888, 2013). "Women with ovarian cancer have higher levels of CTSB in their sera, and CTSB is present in ascites and cyst fluid of patients with ovarian cancer." (PMID 20727192, 2010). "Again, malignant ovarian tumor cystic fluid had considerably greater cathepsin B and C levels." (PMID 36574159, 2022). "Interestingly, stage I ovarian carcinoma showed a trend to increased expression of cathepsin B mRNA compared to normal tissue." (PMID 31484396, 2019). "Therefore, ovarian carcinoma was used as a model system for further investigation, supported by findings of a larger scale study on cathepsin B mRNA expression in malignant ovarian carcinoma compared to healthy tissue." (PMID 31484396, 2019). "In conclusion, bortezomib may induce ERK phosphorylation to suppress cathepsin B and inhibit the catalytic process of autophagy in ovarian cancer and other solid tumors." (PMID 25375375, 2014). "Procathepsin B was a pro-form of active mature form of cathepsin B and could be suggested as a new tumour biomarker in ovarian cancer." (PMID 23986888, 2013). "CTSB is a marker for ovarian cancer prognosis and may contribute to the invasion of ovarian cancer cells." (PMID 20727192, 2010). "Moreover, immunohistochemical analysis has shown that CTSB is evident in the cytoplasm of tumor cells in human ovarian cancer." (PMID 20727192, 2010). "We characterized the ovarian cancer cell lines OVCAR-3 and OVCAR-5 for their cathepsin B expression." (PMID 31484396, 2019). "In these two ovarian carcinoma cell lines, namely OVCAR-3 and OVCAR-5, the mRNA expression of cathepsin B was comparable, even if lower than in the human tissue samples." (PMID 31484396, 2019). "The results of the present study demonstrate that CTSB, CTSC, and CTSS are upregulated in cancerous ovaries of chickens, suggesting that CTSB, CTSC, and CTSS have potentially important functions in the development of ovarian cancer in chickens." (PMID 20727192, 2010). "Our results suggest that CTSB, CTSC, and CTSS have important functions in the development of epithelial ovarian cancer." (PMID 20727192, 2010). "Thereinto, thyroid and ovarian cancers had significantly high CTSB expressions than the matched normal tissues." (PMID 35155389, 2022). "These include CTSB in OAC, BAIAP2L1 in ovarian cancer and BCAR1 in a range of cancers." (PMID 28859074, 2017). "Exposing vesicles released by ovarian cancer cells (CABA1) to acidic medium increased MMP-2 and MMP-9 activities; this effect was abolished by the specific inhibitor of cystein protease or by silenced expression of cathepsin B in CABA1 cells." (PMID 28317069, 2017). "Indeed, CTSB, SERPINB11, A2M, and PTN are genes that we reported to be most abundant in the GE of ovarian cancers in laying hens." (PMID 23843947, 2013).
ovarian cancer (continued). "Although bortezomib treatment increased p62 levels in all of eight studied ovarian cancer cell lines, the changes in phospho-ERK and cathepsin B were not consistent in few ovarian cancer cell lines, suggesting that additional regulatory mechanisms for cathepsin B exist." (PMID 25375375, 2014). "Six small molecules, including bortezomib (proteasome inhibitor), CA-074-Me (cathepsin B inhibitor) and 17-AAG (HSP90 inhibitor), synergized with cisplatin specifically in FA-proficient ovarian cancer cells (2008 + FANCF), but not in FA-deficient isogenic cells (2008)." (PMID 22537224, 2012). "In this study, we discovered that QC significantly upregulates cathepsin L (CTSL) but not CTSB and CTSD, implicating the specific role of CTSL in promoting QC-induced autophagic flux in ovarian cancer." (PMID 33919392, 2021).
Cognitive impairment (13 papers, 2012 to 2025). Abnormal cognition is characterized by deficits in thinking, reasoning, or remembering. "The combination of serum miR‐96‐5p and CTSB as potential biomarkers for cognitive impairment significantly enhanced diagnostic sensitivity and specificity." (PMID 40919134, 2025). "Abnormalities in the miR‐96‐5p/CTSB signaling pathway were detected in the serum of both mild cognitive impairment and AD patients, and the combination of serum miR‐96‐5p and CTSB demonstrated strong diagnostic efficacy for cognitive impairment (AUC = 0.7536)." (PMID 40919134, 2025). "Overexpression of CTSB in hippocampal neurons of WT mice also promoted astrocyte reactivity and resulted in AD‐like cognitive impairment." (PMID 40919134, 2025). "To further elucidate the alterations in miR‐96‐5p/CTSB levels in the serum of AD patients, we collected serum samples from 48 healthy controls (HC), 30 mild cognitive impairment (MCI) patients, and 52 patients with mild to moderate AD." (PMID 40919134, 2025). "They found that adults with cognitive impairments have lower Cathepsin B (CTSB) levels in the brain, and aerobic exercise training elevated these levels and improved memory function." (PMID 39338076, 2024). "Evaluation by this review of findings in the literature indicate that elevated CTSB correlates with cognitive deficits in AD patients." (PMID 36970896, 2023). "In this study, we found that genetic ablation of cathepsin B (CatB) in mice significantly reduced the generation of reactive oxygen species (ROS) and neuroinflammation and improved cognitive impairment during aging." (PMID 30575263, 2019). "Nonetheless, these results suggest that cathepsin B is upregulated in the brains of HIV-infected individuals with cognitive impairment." (PMID 22693552, 2012). "The combination of serum miR‐96‐5p and CTSB represents potential serum biomarkers for cognitive impairment, and targeting the neuronal miR‐96‐5p/CTSB pathway may serve as a promising therapeutic strategy for AD." (PMID 40919134, 2025). "Importantly, the rise in cathepsin B has been correlated with dementia scores and cognitive impairment in the Mini-Mental State Examination (MMSE) in AD patients." (PMID 39544403, 2024). "The numerous studies of CTSB KO demonstrate that CTSB participates in memory deficits and Aβ production in hAβPP-695 models, combined with clinical data showing correlation of elevated CTSB with cognitive deficits, support the conclusion that CTSB participates in AD memory deficits and pathology." (PMID 36970896, 2023). "In patients with mild cognitive impairment (MCI), plasma levels of cathepsin B were similar to those of controls." (PMID 39544403, 2024). "In addition, further study of cathepsin B expression in the brains of HIV-infected individuals with and without cognitive impairment will be necessary to confirm the role of cathepsin B in HAND." (PMID 22693552, 2012).
malaria (12 papers, 2008 to 2023). Malaria is a serious and sometimes fatal disease caused by a parasite that commonly infects a certain type of mosquito which feeds on humans. "The S2 pocket of longipain contains Asp332, like the human malaria parasite cathepsin L. Longipain was found to be most similar in sequence architecture to the known spider cathepsin B from Araneus ventricosus, with 64 % similarity." (PMID 18483546, 2008).
thyroid cancer (12 papers, 2011 to 2025). "Further, among thyroid cancer patients, increased CTSB expression was related to higher risk of lymph node metastasis (LNM) and advanced N stage." (PMID 33333840, 2020). "Even though previous studies have reported on the level and localization of CTSB in thyroid cancer, the underlying mechanisms of action remain unknown." (PMID 33333840, 2020). "However, cathepsin B is the most likely candidate since this proteinase is frequently found to be increased in cancer and is thought to contribute to invasive and metastatic properties of cancer, and it has also been previously associated with thyroid cancer." (PMID 38203548, 2023). "CTSB overexpression induced cell migration by enhancing vimentin and Snail expression in thyroid cancer cell lines." (PMID 37576397, 2023). "Here we reveal this mechanism to be a metastasis process via p38 activation and also show that it is regulated by CTSB secreted from thyroid cancer cells." (PMID 33333840, 2020). "Overexpression of CTSB in thyroid cancer cell lines activated cell migration by increasing the expression of vimentin and Snail, while its siRNA-mediated silencing inhibited cell migration by decreasing vimentin and Snail expression." (PMID 33333840, 2020). "Taken together, these results indicate that altering cellular levels of CTSB can affect epithelial–mesenchymal transition (EMT) activation in thyroid cancer cell lines." (PMID 33333840, 2020). "We similarly demonstrate that low levels of CTSB inhibit cell migration through decreased expression of vimentin or Snail in thyroid cancer cell lines." (PMID 33333840, 2020). "To explore the relationship between the CTSB expression level and clinicopathologic features in thyroid cancer, we analyzed the expression levels of CTSB in 158 pairs of Korean PTC patients (tumor tissue vs. adjacent nontumor tissue) using Western blotting." (PMID 33333840, 2020). "To explore the mechanism underlying the effects of secreted CTSB during EMT progression, we analyzed changes in cellular signaling pathways in CTSB-treated thyroid cancer cell lines." (PMID 33333840, 2020). "Recently, we have determined that cathepsin B is the main active cysteine cathepsin present in the human thyroid carcinoma cell lines KTC-1, HTh7 and HTh74 cells." (PMID 21835049, 2011). "Transport of endogenous and eGFP-tagged active and inactive cathepsin B in the cultured thyroid carcinoma cells reflected the distribution patterns of this protease in thyroid carcinoma tissue." (PMID 21835049, 2011). "Analysis of chimeric protein trafficking further showed that GFP-tagged cathepsin B was transported to the expected compartments, i.e. endoplasmic reticulum, Golgi apparatus and endo-lysosomes of normal and thyroid carcinoma cell lines." (PMID 21835049, 2011). "Moreover, in individuals with thyroid cancer, heightened levels of CTSB were positively correlated with lymph node metastasis (LNM) and advanced N staging, suggesting its possible involvement in the advancement and metastatic dissemination of the condition." (PMID 39791166, 2025). "In thyroid cancer, CTSB localizes to the basement membrane and induces EMT by altering the ECM." (PMID 37576397, 2023). "Our results reveal that CTSB may not only be a potential prognostic marker of metastasis but also function as a new target for antimetastatic cancer drugs in thyroid cancer." (PMID 33333840, 2020). "The mechanisms of CTSB action in thyroid cancer are unknown and our investigation of the same revealed that CTSB overexpression induces cell migration by enhancing the expression of vimentin and Snail in thyroid cancer cell lines." (PMID 33333840, 2020). "Analysis of patient samples showed that upregulation of CTSB was associated with LNM; therefore, we hypothesized that changes in CTSB expression can affect metastasis in thyroid cancer." (PMID 33333840, 2020).
thyroid cancer (continued). "Similarly, thyroid carcinomas with extracapsular invasion and metastasis that showed higher CTSB activity also exhibited higher type I and IV collagen degradation abilities." (PMID 27031837, 2016). "However, cathepsin B has also been localized to the extrafollicular space in thyroid cancer tissue, and is therefore suggested to promote invasiveness and metastasis in thyroid carcinomas through e.g. extracellular matrix degradation." (PMID 21835049, 2011). "However, cathepsin B has also been shown to be localized to the basement membrane of thyroid carcinoma cells in situ, where it was proposed to facilitate tumor invasiveness and metastasis through degradation of the extracellular matrix." (PMID 21835049, 2011). "The cathepsin B-eGFP and cathepsin B-C29A-eGFP chimeric proteins were not only expressed in normal thyrocytes and in thyroid carcinoma cells, rather cathepsin trafficking was also investigated in combination with the activity based probe GB117 in order to specify its sorting into transport vesicles." (PMID 21835049, 2011). "In addition, the active site mutant counterpart of cathepsin B was sorted into endocytic compartments of the thyroid carcinoma cell line HTh74." (PMID 21835049, 2011). "Next, we were interested to determine whether cathepsin B trafficking is altered in thyroid carcinoma cells in comparison to normal thyroid epithelial cells." (PMID 21835049, 2011). "This notion motivated us to analyze the pathways resulting in altered cathepsin B trafficking and leading to its secretion into the extrafollicular space, which most probably enhances the invasive potential of thyroid carcinoma cells due to cathepsin B's ability to degrade ECM components." (PMID 21835049, 2011). "(ii) As an alternative explanation of re-routing of cathepsin B transport in thyroid carcinoma cells, it was tested whether cathepsin B can be transported differently when expressed in normal epithelial cells versus tumor-transformed cells." (PMID 21835049, 2011). "Thus far, there is scant research on CTSB and thyroid cancer." (PMID 33333840, 2020). "We therefore propose that cathepsin B transport to the basolateral plasma membrane domain and its secretion into the extrafollicular space as observed in follicular and papillary thyroid carcinoma tissues are features of altered trafficking routes in thyroid cancer." (PMID 21835049, 2011). "In conclusion, we developed a novel seven-mRNA (CDKN2A, FGF7, CTSB, HAP1, DAPK2, DNAJB1, ITPR1) risk model and nomogram that could help assess the prognosis of patients and guide clinical decision-making and individualized therapy for differentiated thyroid cancer." (PMID 35459137, 2022). "Our investigations on the role of secreted CTSB during thyroid cancer metastasis show activation of the p38 pathways without any involvement of the ERK and JNK pathways (data not shown) or cell cycle-related factors (data not shown)." (PMID 33333840, 2020). "The relationship between CTSB and thyroid cancer is not known, and this study investigated differential CTSB expression, if any, in the secretome of a PTC cell line and compared it with that seen in a normal thyroid cell line." (PMID 33333840, 2020). "As our results suggest that elevated CTSB in thyroid cancer induces the expression of metastatic proteins and thereby leads to LNM, CTSB may be a good and clinically relevant prognostic marker." (PMID 33333840, 2020). "This fact, together with the suggested role of cathepsin B in malignant progression, prompted us to further analyze trafficking of cathepsin B in KTC-1 cells, a poorly differentiated papillary thyroid carcinoma cell line, and in the anaplastic HTh7 and HTh74 thyroid carcinoma cell lines." (PMID 21835049, 2011). "In this study, we showed that specific transport signals within the sequence of cathepsin B are unlikely to exist that would explain why thyroid carcinoma cells transport the cysteine protease differently than normal thyroid epithelial cells." (PMID 21835049, 2011).
thyroid cancer (continued). "Cathepsin B was shown by immunostaining to be localized within vesicular structures located close to the apical plasma membrane in the non-altered areas of thyroid carcinoma tissue (arrows)." (PMID 21835049, 2011). "Therefore, we identified CTSB as a potential key regulator of PTC and hypothesized that changes in CTSB expression affect thyroid cancer progression." (PMID 33333840, 2020). "Furthermore, secretion of endogenous cathepsin B and of other cysteine peptidases, which occurs at the apical pole of normal thyroid epithelial cells, was most prominent and occurred in a non-directed fashion in thyroid carcinoma cells." (PMID 21835049, 2011). "We have previously shown that cathepsin B is one of the main if not the major cysteine peptidase active in KTC-1, HTh7 or HTh74 cells, and that its predominant expression pattern is vesicular in these thyroid carcinoma cell lines." (PMID 21835049, 2011).
amyloid (11 papers, 2016 to 2025). "AD brains are characterized by Aβ deposits and lysosomal dysfunction, including amyloid plaques enriched with lysosomal hydrolases, such as Cathepsin B and D66." (PMID 38853828, 2024). "In the hAβPP-695/Wtβ-Lonγ AD model, CTSB KO substantially reduced Aβ peptide levels and amyloid plaque pathology." (PMID 36970896, 2023). "Cathepsin B cleaves SAA at residues 76–77 to produce the most common form of AA found in amyloidosis." (PMID 36240260, 2022). "Their investigation in vivo remains limited, though cathepsin B has been observed in amyloid plaques." (PMID 35573838, 2022). "Besides, an increase in the activity and expression levels of cathepsin B (CTSB) was found to correlate with increased amyloid plaque deposition." (PMID 39122455, 2024). "Furthermore, CTSB itself has been detected in the amyloid deposits of patients." (PMID 39955315, 2025). "Thus, considering the results obtained, it can be hypothesized that in the case of CTSB application in anti-amyloid therapy, the enzyme will exhibit a universal dual mechanism of action on fibrils regardless of the pathology and type of amyloids causing it." (PMID 39955315, 2025). "Notably, CTSB accumulates with amyloid plaques in human AD brain." (PMID 36970896, 2023). "Although cathepsin B accumulates in close proximity to NFTs and amyloid plaques, there is no direct evidence that this protease can cleave tau." (PMID 35573838, 2022).